H2AX (H2A.X variant histone)
Diseases named in the same sentence as H2AX in open-access papers (continued):
Sharing a sentence is not in itself a finding about the gene and the disease.
tumor (continued). "The data implied that the degradation of γ‐H2AX was delayed after treatment with TPP‐LND@Lip, while no such delay was observed in the control groups, indicating that the DDR function of tumor cells was impaired and depressed." (PMID 37092578, 2023). "We indeed observed a significant increase in γH2AX (phosphorylated histone H2AX)‐positive cells in 5‐ALA and dihydroartemisinin double‐treated GFP‐positive tumor tissue, but not in the control wild‐type cells (Fig EV3E and F)." (PMID 36740985, 2023). "The majority of published works that focused on the role of γ-H2AX foci as a biomarker to predict tumour radiosensitivity were conducted in vitro or in HNSCC tumour xenograft models and not in a clinical study." (PMID 35055060, 2022). "Phosphorylation of histone H2AX (pH2AX), a marker for DSB, in dissected tumours and corresponding liver tissues was not significantly different between Ccne1f/f and Ccne1−/− mice at week 40 after DEN." (PMID 34830835, 2021). "Moreover, tumor lysates obtained from LoVo and SW480 xenograft mice treated with SSa for 10 days also showed H2AX phosphorylation (data not shown)." (PMID 29245990, 2017). "Consistently, exposure of mice to AZD6738 significantly enhanced the percentage of tumor cells that stained positive for phosphorylated KAP1 and H2AX in CTR9-depleted tumors while treatment of control animals with AZD6738 did not induce a significant increase in KAP1 or H2AX phosphorylation." (PMID 38365788, 2024). "In the A549 xenograft tumor model, we showed that 4-CBA treatment moderately inhibited tumor growth, and combining 4-CBA with RT markedly suppressed tumor growth, which correlated with increased 4-HNE staining (but not with phospho-H2AX or cleaved caspase-3 staining) in these tumor samples." (PMID 35459868, 2022). "Furthermore, the overall levels of γ-H2AX were higher in MSI CRC cell lines expressing UVRAGFS compared with the WT counterparts, and likewise, were significantly different between UVRAGFS-positive and -negative primary tumours." (PMID 26234763, 2015).
cancer (319 papers, 2007 to 2026). A tumor composed of atypical neoplastic, often pleomorphic cells that invade other tissues. "Cancer develops through an increased expression in Phospho-H2AX, which leads to increased DNA damages and mutations." (PMID 40004944, 2025). "Radiation therapy causes DNA damage in cancer cells, leading to the activation of their natural DNA repair mechanism involving the phosphorylation of H2AX into rH2AX, which recruits DNA repair proteins to the damaged site." (PMID 39224810, 2024). "It is reported that mice with H2AX gene knockout have increased genomic instability and higher cancer risk." (PMID 35903980, 2023). "Some studies have evaluated cancer cell DNA strand breaks caused by CAP treatment by detecting the phosphorylated form of histone H2AX: γ H2AX." (PMID 35646968, 2022). "H2AX is a histone variant that belongs to the H2A family and prevent genome instability and cancer, while the phosphorylated form γH2AX is regarded as a robust marker of DNA double-strand breaks (DSBs)." (PMID 35721721, 2022). "Meanwhile, the expression of H2AX, an identified driver gene associated with gene instability and cancer onset, was compared between the two groups." (PMID 34880908, 2021). "Changes in transcript expression of DNA repair and damage genes were associated with an increased expression of phosphorylated-H2AX, a marker for DNA damage, at advanced cancer stages." (PMID 34669013, 2021). "This was also associated with a substantial increase in γ-H2AX expression in most of the cancer cell lines treated with 2-APCAs." (PMID 33503939, 2021). "Upregulation of pBCLAF1 (Ser290) was found in association with irradiation-induced γ-H2AX expression in the nucleus, leading to an increased DNA damage repair response, and a marked inhibition of irradiation-induced cancer cell apoptosis." (PMID 34372878, 2021). "Although it is widely known that increased DDR is closely associated with intrinsic radioresistance in cancer cells, there is very little data indicating a role for H2AX monoubiquitination in the radioresistance of HCC cells." (PMID 33087136, 2020). "Radiation therapy kills cancer cells by causing breaks in the DNA strands, which is indicated by the rapid phosphorylation of histone H2AX at serine 139 (γ-H2AX) and cleavage of poly (ADP-ribose) polymerase (c-PARP)." (PMID 31216782, 2019). "H2AX gene is frequently lost in cancer, and H2AX deficiency can lead to increased sensitivity to ionizing radiation, which exhibit genomic instability and enhanced susceptibility to cancer." (PMID 30806885, 2019). "Persistence of γ-H2AX after radiation is reported as a marker for radiosensitivity of cancer cells and γ-H2AX loss is relatively faster in radioresistant cell lines." (PMID 30893896, 2019). "Protein methyltransferase SUV39H2 was reported to methylate histone H2AX at lysine 134 and enhance the formation of phosphorylated H2AX (γ-H2AX), which causes chemoresistance of cancer cells." (PMID 30159125, 2018). "Immunodetection of γ-H2AX is used to quantify DNA damage in cells and tissues, and has diagnostic and prognostic value in cancer." (PMID 30622513, 2018). "A large series of studies have aimed to demonstrate correlations between post-irradiation γ-H2AX responses and acute and late radiosensitivity, or radiation-induced cancer risk, across a large variety of cancer patient cohorts, with mixed results." (PMID 29077012, 2017). "These protein function-affecting gene patterns provide an indication of the mutational status of the cancer cell lines in their untreated state, and the findings suggest that increased % γ-H2AX values correspond to high mutational burden." (PMID 28158293, 2017).
cancer (continued). "Conversely, ALDH1A1 depletion in A2780/CP70 cells resulted in robust increase of BRACA1 protein in association with γ-H2AX induction, demonstrating altered regulation of DNA damage response and repair networks in cancer stem-like cells." (PMID 25216266, 2014). "The protein H2AX plays a vital role in cellular functioning: Its serine phosphorylated form, -H2AX, is one of the earliest repair responses to DNA double-strand breaks which can lead to mutations that in turn are a cause of cancer and hereditary disease." (PMID 22442661, 2012). "Depletion of Cdc7 in HeLa, U2OS or other cancer cells with siRNA resulted in inhibition of DNA synthesis, accumulation of chromosome damages [represented by γ-H2AX foci) and eventual loss of viability viability." (PMID 22574151, 2012). "MSH3-deficient cancer cells maintain higher levels of phosphorylated histone H2AX and 53BP1 after oxaliplatin treatment in comparison with MSH3-proficient cells, suggesting that MSH3 plays an important role in repairing DNA double strand breaks (DSBs)." (PMID 23209772, 2012). "The histone variant H2AX plays functional role in DNA repair and genome stability and hence cancer susceptibility while histone H2B was reported to be involved in the post-replication DNA repair." (PMID 20419108, 2010). "CBMN, comet, and H2AX foci assays showed that SSa caused significant DNA damage in cancer cells." (PMID 29245990, 2017). "Furthermore, utilizing the NCI-60 cancer cell line panel, we show a correlation between the basal fraction of γ-H2AX and cellular mutation levels." (PMID 28158293, 2017). "However, the detailed mechanism underlying the association of H2AX with apoptosis in cancer cells remains elusive." (PMID 27780918, 2016). "However, the mechanism underlying the association of H2AX with apoptosis in cancer cells remains elusive." (PMID 27780918, 2016). "Here, we tested whether stalling of DNA replication, a common event in cancer cells and the underlying mechanism of various chemotherapeutic agents, can trigger increased soluble H2AX." (PMID 18616816, 2008). "CMRP-induced increase in the levels of the phosphorylated form of histone variant, γ-H2AX, provided compelling and corroborative evidence of DNA damage, whilst reduction in cyclin B1 and Chk1 expression was indicative of the extract’s ability to influence the cell cycle of cancer cells." (PMID 33436696, 2021). "As with the THP1 experiments, measurements of the NCI-60 cell lines demonstrated elevated endogenous γ-H2AX levels in cancer cells compared to normal cells, supporting the hypothesis that increased DNA damage is a hallmark of genomic instability in cancer development." (PMID 28158293, 2017). "It is reported that suppression of PFKFB3 or drug inhibition of PFKFB3 increases γ‐H2AX expression but decrease RAD51 expression in some cancer cell types." (PMID 41292194, 2025). "Western blotting showed that combinatorial treatment leads to a decrease in Phospho-H2AX levels, which prevents the formation of cancer cells." (PMID 40004944, 2025). "We observed that, consistent with findings in cancer cells, sunitinib also induced DNA damage in hiPSC-ECs, as indicated by an increase in the percentage of γ-H2AX–positive cells." (PMID 39895626, 2025). "Since platinum typically leads to cancer cell death by inducing DNA damage, we used immunofluorescent labeling of the DNA damage marker protein γ-H2AX to observe carboplatin-induced DNA damage." (PMID 38740757, 2024). "Although H2AX was described to distribute randomly on chromatin, another study in cancer cells found H2AX overrepresented at heterochromatin compared to euchromatin." (PMID 38247831, 2024). "In this study, we found that SAHF produced by fibroblasts, during cellular senescence, inhibits γ-H2AX formation, providing an opportunity to design targeted cancer therapies." (PMID 38542327, 2024).
cancer (continued). "Immunofluorescence images revealed a considerable increase in γ-H2AX adducts (pink dots) following TMZ treatment in cancer cells only, further amplified in the TMZ + CPZ combination." (PMID 39026284, 2024). "After treatment with TUG1 ASO for 24 h, FCM showed significant decrease in DNA replication rate (i.e. EdU incorporation) and increased numbers of γ-H2AX-positive cells in the S phase of HeLa/Fucci2 and other cancer cell lines." (PMID 37607907, 2023). "Compared with FKN and FPN groups upon light irradiation, FKPN obviously increased phosphorylation of γH2AX (a DSB marker positively correlated with early transformation and genomic instability) and the ratio of γH2AX/H2AX within cancer cells." (PMID 37031242, 2023). "The DNA damage response (DDR) performs an integral function in the radiosensitivity of cancer cells with radiation treatment, and phosphorylation of H2AX on Ser139 (γH2AX) around DNA DSBs is a sensitive molecular marker of DDR." (PMID 35426246, 2022). "To verify the ability of the two cancer cell lines to detect double-strand breaks (DSBs), we assessed the phosphorylation of H2AX (γH2AX), an early event of the DNA damage response (DDR), by flow cytometry after 6 hr and 12 hr of treatment with both agents." (PMID 36043458, 2022). "From confocal images, those cancer cells treated with only Zn2+ or Fu showed the obvious γ-H2AX stained fluorescence signals, in contrast with PBS group, which indicated the disturbed DNA transcription." (PMID 36168615, 2022). "The results showed that treatment with I-C19 increased the number of γ-H2AX foci in the cancer cell lines compared with the vehicle." (PMID 36080216, 2022). "Phosphorylation of histone H2AX was also assessed to monitor DNA damage in cancer cells undergoing mitosis." (PMID 35511434, 2022). "The results showed that the expression of γ-H2AX in cancer cells treated with ligustilide was higher than that in the control group (DMSO treatment) at both 24 h and 48 h after irradiation." (PMID 35494068, 2022). "Intravenous injection of dying cancer cells into mice led to activation of both H2AX and inflammatory cytokines in cells of target organs." (PMID 33530310, 2021). "The radiosensitization of QD-RGD and QD-Cat-RGD was further confirmed by p-H2AX staining, which reflected the DNA damage of cancer cells." (PMID 34887404, 2021). "Other epigenetic modifications, such as H2AX phosphorylation, served as an early marker for DNA damage in cancer predictivity." (PMID 34371611, 2021). "In cancer, apigenin has anti-proliferation, cell cycle arrest, and activation of ataxia telangiectasia-mutated (ATM) and H2AX-induced cancer cell apoptosis." (PMID 34356663, 2021). "Several studies reporting phosphorylation of H2AX with CAP treatment in different cancer types have thus concluded that plasma-generated ROS induce DNA damage." (PMID 34502492, 2021). "The phosphorylation of serine at the C-terminus of a DNA double-strand break marker H2A histone family member X (H2AX), eventually contributes to genomic instability leading to cancer." (PMID 34858475, 2021). "In a previous study, we have shown that delivery in cells of antigen-binding fragments (Fabs) derived from an anti-γ-H2AX monoclonal antibody (mAb) allows the fate of cancer cells after treatment with varying RS-inducing drug combinations to be followed." (PMID 34282773, 2021). "For example, studies have found that the downregulated expression of circRNA circ-Ccnb1 in breast cancer can interact with Bclaf1 in cancer cells through H2AX, resulting in the inhibition of uncontrolled division and growth of cancer cells." (PMID 33884267, 2021).
cancer (continued). "Co-cultivation of irradiated dying human cancer cells with mouse fibroblasts not only resulted in activation of H2AX but also to that of multiple inflammatory cytokines in the fibroblast cells." (PMID 33530310, 2021). "Adavosertib therapy has been shown to increase p-CHK1 (Ser345) and p-H2AX (Ser139) levels, two markers of DNA damage in cancer cells." (PMID 34298699, 2021). "For evaluating the extent of double-strand breakage which represents a higher correlation to the genesis of cancer, both γ-H2AX-positive cells and mean fluorescence intensities in γ-H2AX-positive cells were analyzed." (PMID 33284367, 2020). "We have also observed that UBR5 interacts with DNAPK, a molecule known to be activated during DNA damage responses, which further supports a role for UBR5 in ATM and DNA-PK mediated H2AX-phosphorylation, as well as cancer development and progression." (PMID 32867711, 2020). "The application of γ-H2AX antibodies to the amplified γ-H2AX, results in discrete foci appearing at sites of ds breaks within the nucleus and its use as a biomarker in cancer chemotherapy is emerging." (PMID 32887437, 2020). "It seems likely that the upregulation we have seen in H2AX is related to crosstalk with the cancer microenvironment, ostensibly preconditioning the adjacent normal tissue." (PMID 32887437, 2020). "The overload of RONS in CCA cells leads to DNA damage, attested by the phosphorylation of histone H2AX, triggering pathways that will ultimately kill the cancer cells." (PMID 32438553, 2020). "This was evidenced by substantial decrease of Rad51 foci that were co-localized with γ-H2AX when cancer cells were treated with Dox in presence of AKT inhibitor." (PMID 33266502, 2020). "The genotoxic effect of this nanodevice in cancer cells was confirmed by nucleus histone H2AX specific immunostaining." (PMID 32492910, 2020). "Another important potential application of γ-H2AX assay is the assessment of individual radiosensitivity of prospective patients by monitoring normal tissue responses in parallel with the clinical cancer outcome." (PMID 32372284, 2020). "Double‐strand breaks are considered to be the most cytotoxic molecular events to cancer cells, and γ‐H2AX is a biomarker of these breaks." (PMID 32022328, 2020). "The human H2AX gene (H2AFX) maps to chromosome 11 at position 11q23, in a region that frequently exhibited mutations or deletions in a large number of human cancers." (PMID 32175564, 2020). "A relatively new biomarker has been used recently, the γ-H2AX, to assess DNA double-strand breaks in cancer research." (PMID 31529301, 2020). "Two key proteins, H2AX and Bclaf1, which function in DNA repair and cell mitosis, play roles in cancer development." (PMID 32194627, 2020). "Previously, we have shown that in vivo inhibition of the functions of either PCNA or DNA polymerase alpha (which are key components of the replisome) by antibodies, strongly induced RS and the consequent phosphorylation of H2AX in cancer cells." (PMID 30871194, 2019). "In any case, we report here that the reduction of Claspin and Timeless levels in cancer cell lines reduced the speed of fork progression, increased the rate of fork stalling and increased γ-H2AX levels in checkpoint-proficient cells." (PMID 30796221, 2019). "A previously reported study suggested miR-3196 to be a target of the tumour suppressor protein H2AX, and that the combination of its promoter and phosphorylated H2AX (γH2AX) can promote cancer cell apoptosis." (PMID 31235820, 2019). "In recent years, the γ-H2AX biomarker has become a powerful tool to monitor DNA DSBs in translational cancer research with the potential to assess the radiosensitivity of prospective radiotherapy patients." (PMID 31438980, 2019). "In our study, CLA derivatives increased H2AX level in tested cancer cell lines in a manner dependent on the drug sensitivity of the cells." (PMID 31575977, 2019).